EGFR (epidermal growth factor receptor)
Diseases named in the same sentence as EGFR in open-access papers (continued):
Sharing a sentence is not in itself a finding about the gene and the disease.
cancer (continued). "Experimentally altering specific EGFR-related genes and pathways caused autophagic cell death or growth, suggesting the crucial role of autophagy in the sensitivity and resistance of cancer cells to EGFR-TKIs." (PMID 35690866, 2022). "EGFR inhibitors also activate nuclear factor-κB in both cancer and normal cells, leading to destruction of immune balance and an inflammatory microenvironment." (PMID 35223483, 2022). "Presently, the aberrant expression of the EGFR and activation of EGFR-mediated downstream signaling pathways have been seen in a large number of human malignant tumors, including HCC." (PMID 35624643, 2022). "The CLDN6 gene acted as the oncogene in HCC and enhanced cancer cell invasion, migration, and proliferation through EGFR/AKT/mTOR signaling pathway." (PMID 35150083, 2022). "The massive expression of MUC1 and EGFR demonstrated the purity of cancer cells in the organoid-derived xenograft model." (PMID 36340504, 2022). "We demonstrate that both functional and non-functional fusion oncogenes in terms of drug resistance are present in EGFR mutant cancers as detected by DNA-based NGS." (PMID 36153311, 2022). "They found that FAM83A and FAM83B are candidate cancer-related genes that can develop FAM83 resistance to EGFR-TKIs." (PMID 35938024, 2022). "The experience and knowledge gained in the clinical development of ERBB1/EGFR-targeting FDA-approved therapeutics as precision medicines against other human cancer types should facilitate their development as potential precision medicines against MM as well." (PMID 36311273, 2022). "MiR-146b from MSC exosomes binds to EGFR mRNA, and eventually reduced the growth, migration, and invasion of cancer cells in culture." (PMID 36114463, 2022). "α2-6-Sialylation of epidermal growth factor receptor (EGFR) regulates the epithelial-to-mesenchymal transition (EMT) of cancer cells and sustains its membrane retention, regulating integrin tension, focal adhesion, and cell motility." (PMID 36497322, 2022). "The promising coumarin derivatives 10, 13 and 15 derivatives against Paca-2, Mel-501, PC-3 and A-375 cancer cell lines were further assessed for their inhibitory activities against EGFR, VEGFR-2 and CDK-2/cyclin A2 kinases to detect their mechanism of action." (PMID 35408446, 2022). "The reported compounds exhibited significant anticancer and antioxidant activities, as well as displayed significant inhibition against cancer targets, EGFR and CA, in the molecular docking studies." (PMID 35011539, 2022). "A down-regulated expression of VEGFR2 and EGFR was reported in HepG2 cancer cells treated by single and combined treatments of sorafenib and ramucirumab." (PMID 36284117, 2022). "The activated EGFR stimulates the activation of various intracellular signaling pathways that play essential roles in cancer cell proliferation, migration and survival, including the Ras/Raf/Mek/ERK, PI3K/Akt, STAT and Src pathways." (PMID 35999506, 2022). "These include unique cancer patient samples harboring EGFR E709K (n = 67), EGFR E928K (n = 1), ERBB2 E717K (n = 10), ERBB3 E925K (n = 7), ERBB4 E715K (n = 8), and ERBB4 E934K (n = 5) variants." (PMID 36860695, 2022). "Several anti-EGFR monoclonal antibodies have been approved for cancer treatment, including cetuximab, panitumumab, nimotuzumab, and necitumumab." (PMID 36263226, 2022). "Epidermal growth factor receptor (EGFR) represents one of the most known oncogenes and it is frequently up-regulated or mutated in human cancers." (PMID 35955669, 2022). "Constitutive EGFR activation via ligand shedding as well as ligand-independent EGFR transactivation in keratinocytes and some EGFR-dependent cancer cell types including SCC has been reported." (PMID 35185556, 2022).
cancer (continued). "Crosstalk between the M3 receptor and EGFR was suggested for cancer, for instance, in lung enhancing processes, such as proliferation, migration, and invasion due to ACh activity." (PMID 35565451, 2022). "The molecular docking studies of ligands 5a–j were carried out against EGFR (PDB ID: 3W2R) to identify the putative mechanism of action of these ligands against cancer." (PMID 35011539, 2022). "Based on the GO analysis, the target proteins have roles in cancer-related biological processes such as epidermal growth factor receptor signaling pathway, negative regulation of apoptosis, and positive regulation of cell proliferation, among others." (PMID 36106139, 2022). "These engineered CAR-T cells are promising in other cancers overexpressing EGFR including bladder, cervical, esophageal, head, and neck squamous cell, gastric, breast, ovarian, colorectal, endometrial, and non-small lung cell carcinomas." (PMID 35326556, 2022). "Then, we constructed a prognostic index for all cancer samples calculated by the formula IRGRS = expression level of EGFR*0.228279845567824 + expression level of OAS1*(-0.264868237274861)+expression level of MST1R*(-0.167523923476614)." (PMID 36267410, 2022). "Sustained HER3 signaling is a mode of resistance to EGFR-based therapies, and in certain cancers this HER3-dependent signaling can be driven by amplification of MET." (PMID 35325006, 2022). "On the other hand, epidermal growth factor receptor (EGFR) is a theragnostic biomarker in many types of cancer, and its aptamer was conjugated with 18F-fluorobenzoyl (FB) azide for PET scan imaging in mouse models." (PMID 36544906, 2022). "The MAPK signaling pathway has been reported to be activated in cancer drug resistant samples, and its abnormal activation could contribute to cell loss of differentiation and apoptosis, and could be a mechanism of resistance to osimertinib in EGFR-mutated NSCLC." (PMID 35168607, 2022). "As MGL S3 was designed for the precise targeting of EGFR-positive cancer cell lines, we decided to further study the interconnection between EGFR and methionine metabolism." (PMID 36361596, 2022). "EGFR overexpression in cancer tissue samples by immunohistochemistry is significantly associated with the clinicopathological features of CCA and is an independent prognostic factor for poor OS46,47." (PMID 35589822, 2022). "The HCC827 cells were labeled with strong fluorescence, suggesting that CQDs-C225 can specifically target EGFR-overexpressed cancer cells through EGFR-mediated endocytosis, with combined advantages of high sensitivity and good spatial resolution." (PMID 35889495, 2022). "For example, cancer stem cells of salivary AdCC are known as c-kit+, EGFR− cells, but the established cell line includes only EGFR-expressing cells." (PMID 35672412, 2022). "Growth factor receptors (mainly EGFR) and G protein-coupled receptors (GPCRs) mediate a complex signaling network that activates relevant biological effects in cancer cells." (PMID 36558071, 2022). "Secreted HBEGF activates EGFR on the cancer cell surface to induce EMT, resulting in increased migration and invasion in vitro and increased metastasis in vivo." (PMID 36352257, 2022). "It was revealed that DTX containing immunoliposomes functionalized with EGFR antibody had more efficiency against DU145 with higher expression of EGFR, emphasizing the role of EGFR as a target for cancer therapy." (PMID 36559202, 2022). "The increased expression of EGFR in cancer cells was a significant factor in the development of chemo-resistance." (PMID 36338727, 2022).
cancer (continued). "Nevertheless, further studies are required to fully elucidate EGFR activity in DM1, because altered EGFR signaling is associated with human cancers." (PMID 36230978, 2022). "Anti-EGFR antibodies such as cetuximab and panitumumab have been approved for treating different EGFR-positive cancers." (PMID 36145664, 2022). "MEK-ERK signaling is a key pathway downstream of EGFR and mediates EGFR-dependent regulation of cancer cell growth and survival." (PMID 34973117, 2022). "The strength of the study is that we assessed the EGFR and cyclin D1 expression profile from normal cells to cancer cells and then investigated its prognostic capability in GC within the same TNM stage." (PMID 35723316, 2022). "Consistently, MetRes features were enriched in cancer cells from EGFR-mutant NSCLC patients with progressive disease." (PMID 36509758, 2022). "All those targets involved in the signal transduction of the prolactin signaling pathway, central carbon metabolism in cancer, EGFR tyrosine kinase inhibitor resistance, endocrine resistance, and VEGF signaling pathway." (PMID 36408342, 2022). "We reanalyzed that part of the data and compared the expression level of EGFR in cancer and paracanerous tissues." (PMID 36551506, 2022). "Even though EGFR-targeted cancer therapy is initially effective against KRAS-wild-type cancers, drug resistance is prevalent in patients receiving several cycles of treatment, highlighting the urgent need to design novel therapeutic modalities." (PMID 35372044, 2022). "In cancer patients, while immune checkpoint inhibitors are used, EGFR status also provides a new treatment strategy for cancer patients, thus improving clinical outcomes." (PMID 36189266, 2022). "Others have reported that the EGFR/HER2 TKI afatinib sensitizes HNSCC cells to radiation by specifically targeting cancer stem cells." (PMID 35158773, 2022). "To test this prediction, we assessed the phosphorylation status of NELF-A in three representative cancer cell lines harboring various ERK-activating oncogenes: A431 (EGFR amplification), H1299 (NRasQ61K), and A375 (BRafV600E)." (PMID 36463234, 2022). "Yet, to our knowledge, this is the first report on EGFR-targeted liposomes as CPT-11 delivery system for cancer therapy." (PMID 35918704, 2022). "Herein, we review the recent nanobiotechnological advancements that combine the promise of PDT with EGFR-targeted molecular cancer therapy." (PMID 35213974, 2022). "The existence of targetable oncogenic mutations was excluded by utilizing the Illumina amplicon cancer panel (TSACP), sequencing 212 regions in 48 cancer-related genes including EGFR, BRAF, KRAS, MET, and RET." (PMID 35039644, 2022). "A number of phytochemicals are known to address cancer-related target proteins, such as the epidermal growth factor receptor (EGFR) or the nuclear factor-kappa B (NF-κB) and others." (PMID 35409325, 2022). "There are many FDA-approved TKIs and monoclonal antibodies for targeting EGFR in various types of cancers." (PMID 35978801, 2022). "In these NSCLC patients, mechanisms observed in cancers with acquired resistance to first generation EGFR inhibitors have also been identified." (PMID 35884384, 2022). "CL4 (39 mer) binds at high efficacy to EGFR overexpressed on the cell surface in several human cancers, including TNBC." (PMID 35336001, 2022). "SHH dysregulations are capable of inducing the profound impact on the gene expression of EGFR/RAS/RAF/MEK/ERK in different cancer cell lines." (PMID 35538578, 2022). "When more than one susceptibility factor for lethal skin toxicity exists, the treatment of related cancers with EGFR inhibitors should be evaluated early and continuously monitored." (PMID 35223483, 2022).
cancer (continued). "Phosphorylated EGFR also activates the JAK2/STAT3 signalling axis to upregulate the transcription of a variety of proteins involved in the survival of cancer cells." (PMID 35158954, 2022). "Even with the most successful targeted therapies for NSCLC, such as EGFR mutant cancer, adaptive and acquired resistance pose problems for targeted therapies." (PMID 36189421, 2022). "In the modern era of cancer immunotherapy, the impact of EGFR TKI plus NSAIDs in the setting of anti-PD-1/PDL-1 is likely needed to impact clinical practice." (PMID 35158773, 2022). "Examples of the therapeutic uses of antibodies to treat cancer include unconjugated (naked) therapeutic antibodies that block the function of the target proteins such as EGFR and PD-L1 on the surface of cancer cells." (PMID 35328459, 2022). "Another ubiquitin ligase, RNF144A, was reported to exert a positive effect on cell proliferation in EGF-dependent human cancer and immortalized embryonic cell line models, by maintaining EGFR expression." (PMID 35634494, 2022). "Afatinib and Dacomitinib are second-line EGFR TKIs that bind to EGFR permanently and show beneficial effects in cancer therapy, but there have been toxicity concerns due to elevated wild-type EGFR off-target binding." (PMID 35745729, 2022). "EGFR has gained much attention as a clinical marker in GBMs and other cancers due to its reported correlation with survival and response to treatment 15-19." (PMID 35145836, 2022). "The present findings support the feasibility of using EGFR as the therapeutic molecular target and albumin as the carrier for cancer targeted therapy." (PMID 35416106, 2022). "In this clinical study, Mir-16-based microRNA mimics coated with EDV demonstrated the properties of egFR-expressing cancer cells targeted by anti-EGFR-specific antibodies (NCT02369198)." (PMID 36290544, 2022). "The two most commonly recommended biological classes of targeted agents include vascular endothelial growth factor (VEGF) antibodies that inhibit cancer angiogenesis and epidermal growth factor receptor (EGFR) inhibitors that block cancer proliferation." (PMID 35954563, 2022). "EGFR signaling plays a central role in cell proliferation and survival, and aberrant activation of EGFR is known to be a major oncogenic pathway for progression and metastasis of many cancers including SCC." (PMID 35954339, 2022). "For the KEGG pathway, the genes were enriched in microRNAs in cancer, cell adhesion molecules, and EGFR tyrosine kinase inhibitor resistance." (PMID 36176992, 2022). "The epidermal growth factor receptor (EGFR) is an important molecule involved in cancer biology and therapy." (PMID 36189421, 2022). "The EGFR is a tyrosine kinase receptor that is frequently upregulated in several cancers such as lung, colon, head and neck, pancreas and breast." (PMID 35260162, 2022). "We used two HNSCC EGFR overexpressing cancer cell lines for experimental validation: SCC25 and Cal27." (PMID 35154483, 2022). "EGFR is frequently overexpressed in cancer, leading to uncontrolled signal transduction and to oncogenic phenotypes." (PMID 35884410, 2022). "The conjugates were characterized by excellent phototheranostic activity, with high phototoxicity against EGFR-expressing cells, allowing imaging of cancer cell lines and human biopsies." (PMID 35213974, 2022). "While several groups have explored the targeting of oncolytic viruses to take advantage of EGFR upregulation in cancer for increased therapeutic specificity, EGFR inhibitors have not typically been explored to modulate oncolytic virotherapy efficacy." (PMID 35572196, 2022). "Of these same glycoproteins, only the EGFR and α2 integrin correlated significantly with cancer invasive potential." (PMID 35028012, 2022).
cancer (continued). "Human EGF has been shown to retain its ability to bind to EGFR when fused to fd filamentous phage and the display of EGF on phage particles can direct the phage vectors to recognize EGFR-expressing cancer cells." (PMID 36591314, 2022). "Among the target genes, EGFR is epidermal growth factor receptor, which is frequently expressed at high levels in different forms of cancer, and its expression is often positively correlated with cancer progression and poor prognosis." (PMID 36360168, 2022). "Claudin1 mediated enrichment of cancer stem-like cells provides a new axis-of-evil for preferential therapeutic targeting of EGFR-TKI resistance, which has potential clinical consequences." (PMID 35301287, 2022). "One group examined the effects of cetuximab and erlotinib on stem cell sub-populations in HNSCC cell lines, and found that these EGFR inhibitors induced large shifts of cells between the epithelial and mesenchymal cancer stem cell populations." (PMID 35158773, 2022). "In conclusion, we illustrated the role of ZC3H15 as a transcription factor that stabilized the EGFR protein level via inhibiting CBL transcription to promote cancer progression." (PMID 35027542, 2022). "For example, EGFR is a frequently altered oncogene in human cancers, and drugs (including tyrosine kinase inhibitors) targeting EGFR signaling have produced impressive initial patient responses." (PMID 35507881, 2022). "The epidermal growth factor receptor (EGFR), which is involved in cell differentiation, migration as well as cell growth, plays an important role in cancer growth and therapy resistance." (PMID 36106025, 2022). "Despite the critical importance of non-invasive diagnostic tools in reducing cancer mortality, to date, only one cirDNA-based test has been approved by the FDA in 2016—for the diagnosis of somatic plasma EGFR gene mutations." (PMID 35806228, 2022). "METTL3 binds to EGFR mRNA near the stop codon and is responsible for its m6A modification, modulating EGFR mRNA stability in human cancer cells." (PMID 35001873, 2022). "On the other hand, the subset of EGFR signaling in cancer was clearly over-represented in patients three and four, both showing mutated KRAS, and PIK3CA was also affected in the oldest patient (patient four)." (PMID 36005154, 2022). "Epidermal Growth Factor Receptor (EGFR), correlated positively with cancers progression and poor prognosis, was reported highly expressed in different types of tumors." (PMID 34991461, 2022). "Mitogen-inducible gene 6 (Mig-6) is a tumor suppressor gene that plays an important role in many types of cancers by interacting with EGFR." (PMID 35165519, 2022). "In this experiment, free uptake of FAM-B-ASO was monitored in A431 cancer cells exhibiting high EGFR expression levels compared to NHDFs with low EGFR density." (PMID 36499115, 2022). "In EAC cells (OE33, OE19, FLO-1) exposed to 200 μM of acidified BM for 20 min, enhanced cancer cell survival was noted due to EGFR-DNA-PKcs pathway activation via insulin-like growth factor binding protein 2 (IGPBP2)." (PMID 35328735, 2022). "GnRH agonist treatment, using both in vitro and in vivo studies, in various cancers showed a significant downregulation of EGFR." (PMID 35109816, 2022). "Constitutive activation of signaling pathways downstream of EGFR by CK2 contributes to the growth factor independence of cancers, which in turn drives cellular proliferation." (PMID 36009534, 2022). "Targeted nanomedicines and antibody-drug conjugates have also been developed for ERBB1/EGFR-directed treatment of several cancer types." (PMID 36311273, 2022). "As a further step towards increasing our understanding of the role of zinc in NSCLC, we now provide insights into the impact of long-term changes in zinc status upon the EGFR and the expression of cancer-relevant proteins in pulmonary carcinoma cells." (PMID 35216384, 2022).